SMPX (small muscle protein X-linked)
Description:
Plays a role in the regulatory network through which muscle cells coordinate their structural and functional states during growth, adaptation, and repair.
Synonyms: DFNX4; Chisel; Csl; DFN6; MPD7
Tractability: Antibody: the Human Protein Atlas places it where antibodies can reach.
Gene: Protein-coding gene on chromosome X (21,705,978 to 21,758,176, reverse strand). Ensembl gene ENSG00000091482.
Subcellular location (Human Protein Atlas): Plasma membrane
Gene Ontology:
Biological process: striated muscle contraction
Cellular component: costamere; M band; muscle tendon junction; contractile muscle fiber; cytoplasm; nucleus
Gene-disease validity (ClinGen):
ClinGen rates the evidence that SMPX causes each of these diseases.
nonsyndromic genetic hearing loss (X-linked): Definitive.
Homologues: Orthologues: macaque SMPX (100% identical), dog SMPX (95% identical), guinea pig SMPX (95% identical), rabbit SMPX (93% identical), pig SMPX (92% identical), chimpanzee SMPX (84% identical), mouse Smpx (83% identical), tropical clawed frog smpx (77% identical), rat Smpx (69% identical), zebrafish smpx (67% identical).
Diseases named in the same sentence as SMPX in open-access papers:
SMPX is named in the same sentence as 22 diseases in open-access papers, as found by Europe PMC text mining. Sharing a sentence is not in itself a finding about the gene and the disease. The quoted sentences say what the papers report.
hearing loss (10 papers, 2016 to 2024). "Our findings suggest that the missense variants described here cause muscle disease through a gain-of-function mechanism of mutant SMPX, contrasting with the loss-of-function mutations associated with hearing loss." (PMID 33974137, 2021). "Moreover, we demonstrated that inner ear HCs of Smpx-deficient embryos lack of mechanotransduction activity, providing the first possible explanation for the reported cases of SMPX-linked hearing loss in human patients." (PMID 38570547, 2024). "While mutations causing total loss of SMPX have been reported to cause hearing loss, its molecular role and function in skeletal muscle remains largely unknown." (PMID 33974137, 2021). "Collectively, this study is the first to report the role of SMPX in Chinese population and identify a novel frameshift mutation in SMPX that causes not only nonsyndromic late-onset progressive HL, but also congenital hearing impairment." (PMID 28542515, 2017).
deafness (5 papers, 2014 to 2021). An inherited or acquired condition characterized by the complete loss of the ability to hear from one or both ears. "Three known deafness genes, including SMPX, USH2A, and ILDR1, were identified, in which the variants in SMPX and USH2A were predicted to have a high‐to‐medium high impact on the function." (PMID 31478598, 2019). "The hemizygous variant in SMPX (SMPX, NM_014332.2: c.132 + 1G>A) was finally identified as possibly being associated with deafness of the proband." (PMID 31478598, 2019). "Taken together, the variant of SMPX may lead to congenital deafness in males and late onset deafness in females." (PMID 31478598, 2019). "Based on these results, we consider that the SMPX gene may be susceptible to this kind of variation, although two potential causative variations were identified in additional sporadic cases of deafness in this study." (PMID 28542515, 2017). "Our results increase the mutation spectrum of the SMPX gene, enrich the observed phenotypes of SMPX-linked deafness, and may contribute to improve mutation-based genetic counselling for affected families." (PMID 28542515, 2017). "In two sporadic patients with deafness and dumbness, we detected two single nucleotide variations, c.238C>A (HL053, female, p.Leu80Ile) and c.55A>G (M9450, male, p.Asn19Asp), in the SMPX gene." (PMID 28542515, 2017). "Moreover, our findings suggest that SMPX may play an underestimated role in Chinese deafness." (PMID 28542515, 2017).
distal myopathy (5 papers, 2021 to 2025). Distal myopathy refers to a group of muscle diseases which share the clinical pattern of predominant weakness and atrophy beginning in the feet and/or hands. "A multicenter study across several countries identified multiple missense mutations in SMPX associated with a novel form of distal myopathy." (PMID 40725470, 2025). "SMPX was first associated with skeletal muscle disease in 2021, making it one of the most recent additions to the list of genes known to cause distal myopathy." (PMID 39017652, 2024). "Usingdeep phenotyping and high-throughput sequencing, we have identified a novel type of distal myopathy caused by mutations in the Small muscle protein X-linked (SMPX) gene." (PMID 33974137, 2021). "On the contrary, in agreement with our results, it has been recently shown that missense mutations in SMPX were associated with the first X-linked recessive form of distal myopathy in humans, suggestive of the gene playing a role in proper muscle organization." (PMID 34204426, 2021). "Our results demonstrate that missense mutations in SMPX cause a previously unidentified muscle disease, a distal myopathy with some amyloidogenic characteristics of the mutant protein." (PMID 33974137, 2021). "The identification of one common founder haplotype in the Italian/Maltese families and another in the French families suggest that missense variants in SMPX may be a more frequent cause of distal myopathy in these European populations." (PMID 33974137, 2021). "Interestingly, this piece of evidence agrees with the recently reported association between SMPX mutations and distal myopathy." (PMID 34204426, 2021). "Indeed, the authors identified SMPX as a novel disease gene responsible for the first form of distal myopathy linked to the X-chromosome." (PMID 34204426, 2021). "Therefore, considering the genotypic and phenotypic features, the findings presented here suggest that the truncated variants cause X-linked NSHL through loss-of-function of mutant SMPX, in contrast to the gain-of-function mutations associated with distal myopathy." (PMID 39272213, 2024). "Variants in SMPX, DNAJB2, and HSPB6 have been identified as a novel cause of late-onset distal myopathy and neuromyopathy." (PMID 39017652, 2024). "Variations in SMPX causing truncation of the protein product were associated with DFNX4, which resulted in typical audiological profiles before and after the age of 10 years, whereas nontruncated proteins typically led to distal myopathy." (PMID 39272213, 2024).
non-syndromic hearing loss (2 papers, 2017 to 2021). "To date, five X-linked genes have been found to be related to the etiology of non-syndromic hearing loss (NSHL): PRPS1 (DFNX1, OMIM:311850), POU3F4 (DFNX2, OMIM:300039), SMPX (DFNX4, OMIM:300226), AIFM1 (DFNX5, OMIM:300169) and COL4A6 (DFNX6, OMIM:303631)." (PMID 33860785, 2021).
hearing disorder (1 paper, 2021). A disorder characterized by the partial or complete loss of the ability to detect sounds due to damage to the ear structures or inability of the brain to properly interpret or process the auditory signals it receives from the anatomic structures of the ear. "Here we provided a new model to study the precise cellular and molecular mechanisms by which mutations in SMPX cause hearing disorders, paving the way towards the identification of therapeutic interventions." (PMID 34204426, 2021).
Skeletal myopathy (1 paper, 2021). "SMPX is also expressed in the hair cells of the inner ear, and variants causing a loss-of-function cause hereditary progressive non-syndromic hearing loss (NSHL, OMIM 300066) without reported skeletal myopathy." (PMID 33974137, 2021).
X-linked deafness type 4 (1 paper, 2022). "A previous study reported that mutation of SMPX was associated with X-linked deafness type 4." (PMID 34763096, 2022).
muscular disorders (1 paper, 2021). "Therefore, this last surprisingly result makes it worth investigating possible correlations between SMPX mutations and muscular disorders in humans." (PMID 34204426, 2021).
myopathies (1 paper, 2021). "Neither SMPX-positive protein inclusions, nor other SMPX accumulation was observed in any other disease control myopathies with rimmed vacuolar and/or myofibrillar pathology (2 × HMERF, 2 × sIBM, 1 × LGMD1D, 1 × WDM, and 1 × MFM with unknown etiology, data not shown)." (PMID 33974137, 2021).
SMPX also shares sentences with these, for which no sentence is quoted: cardiomyopathy (1 paper); central nervous system disorder (1); connective tissue disorder (1); depression (1); Dystonia (1); Encephalopathy (1); gastric cancer (1); glioma (1); Hearing impairment (1); schizophrenia (1); Visual impairment (1); X-linked deafness (1); X-linked deafness 4 (1).